IL6 (interleukin 6)
Diseases named in the same sentence as IL6 in open-access papers (continued):
Sharing a sentence is not in itself a finding about the gene and the disease.
atherosclerosis (continued). "On the other hand, IL‐6 may contribute to the pathogenesis and progression of atherosclerosis, plaque rupture, platelet aggregation, and intravascular thrombosis, which increase the risk of following stroke events and result in further functional damage." (PMID 37287421, 2023). "The relationship between IL-6 and atherosclerosis is bidirectional." (PMID 37629496, 2023). "These analyses revealed that SGLT-2i treatment substantially reduces not only macrophage infiltration but also the suppression of inflammatory M1 markers, including tumor necrosis factor-alpha, interlukerin-1 (IL-1), and IL-6, which play a significant role in the improvement of atherosclerosis." (PMID 38813008, 2023). "IL-1β knockdown significantly downregulated TNF-α, IL-6, and IL-8, which implied IL-1β cytokine could be a pharmacological target to prevent atherosclerosis induced by cigarette smoke." (PMID 36791122, 2023). "IL-6 can be resident or trapped in arterial walls, playing an important role in the phenotypic determination of plaque macrophages, polarization and shaping of macrophages, and development of vascular intimal hyperplasia and atherosclerosis." (PMID 36982743, 2023). "Because vitamin D signaling reduces the expression of TNF-alpha, IL-6, IL-1, and IL-8 in isolated blood monocytes, it may have an impact on the pathogenesis of atherosclerosis." (PMID 36742396, 2023). "The IL-1β/IL-6 axis is an important signaling pathway for human and murine atherosclerosis." (PMID 36178662, 2023). "Compared with young people, the elderly have significantly increased plasma inflammatory markers associated with vascular diseases such as atherosclerosis, including TNF-α, interleukin-1β (IL-1β), interleukin-6 (IL-6), C-reactive protein (CRP), interferon γ (IFN-γ), MCP-1, and MMPs." (PMID 37894840, 2023). "High blood levels of IL-6 may have an important role in the transformation of macrophage to foam cells in atherosclerosis in CAD patients." (PMID 38017432, 2023). "Our objective was to determine which BBB characteristics are produced mainly by interleukin (IL)-6, an atherosclerosis promoting cytokine, and whether these actions can be antagonized by IL-10, an anti-inflammatory cytokine." (PMID 36882782, 2023). "Apabetalone downregulates IL-6 expression in several cell types, including LPS-stimulated human macrophages, endothelial cells under a variety of inflammatory stimuli, and arterial expression in a murine model of atherosclerosis." (PMID 37371758, 2023). "IL-17, produced by T helper 17 (Th17) lymphocytes, can produce IL-6 by affecting endothelial cells, which may successively result in atherosclerosis, thrombosis, and CVD." (PMID 37992065, 2023). "Studies in this direction have laid the groundwork for the hypothesis that IL-6 could be a therapeutic target for atherosclerosis." (PMID 36836675, 2023). "IL-6, known as a systemic indicator of inflammation, also plays a major role in maintaining the inflammatory state, which acts as a stimulus for the formation of atherosclerosis." (PMID 37998729, 2023). "Recent genetic and MR studies have demonstrated the role of IL-6 in atherosclerosis and CVD." (PMID 37900560, 2023). "The patho-mechanical connection between PCN and atherosclerosis was illustrated, starting from dust inhalation that triggers a prothrombotic activity via the interleukin-6-dependent system, leading to diminished clotting time, intravascular thrombin formation, and accelerated arterial thrombosis." (PMID 36979875, 2023). "More precisely, IL6 is a potent activator of atherosclerosis, while being an up regulator of LIPG8." (PMID 37588971, 2023). "Likewise, inflammation markers such as interleukin-6 (IL-6) and tumor necrosis factor (TNF) are independently associated with adverse cardiac outcomes in people with atherosclerosis." (PMID 37639046, 2023).
atherosclerosis (continued). "This may help to minimize endothelial dysfunction and the pro-inflammatory effect of IL-6, being useful for not only atherothrombotic stroke but atherosclerosis prevention as well." (PMID 37762627, 2023). "Notably, patients with RA are at an increased risk of premature death due to accelerated atherosclerosis in cardiovascular comorbidities, while NLRP3 inflammasome activation and production of IL-1β, TNF-α, and IL-6 are also key immune mediators of RA." (PMID 37720032, 2023). "Interleukins (IL-1β and IL-6), chemokines, interferon-γ (IFN-γ), and tumor necrosis factor-alpha (TNF-α) are the cytokines commonly associated with endothelial dysfunction, vascular inflammation, and atherosclerosis." (PMID 37629526, 2023). "These outcomes could be interesting in the context of atherosclerosis because IL-6 is considered a pro-atherogenic cytokine." (PMID 35887517, 2022). "IL-6 protein levels increased in the blood and bone marrow of mice with atherosclerosis." (PMID 35747128, 2022). "IL‐1 inhibition reduced cardiovascular events in the Canakinumab Antiinflammatory Thrombosis Outcome Study trial, and IL‐6 inhibition has been found to have beneficial effects on markers of atherosclerosis such as carotid intima‐media thickness and to reduce cardiovascular events in RA." (PMID 35583917, 2022). "Additionally, we observed an increase in the secretion of progressive atherosclerosis cytokines, such as IL-6, IL-1β, and TNF-α, in the ox-LDL treated HUVEC supernatants." (PMID 35137664, 2022). "SARS-CoV-2 infection stimulates secretions of IL-1β, interferon-γ (IFN-γ), IFN-γ-induced protein 10kDa (IP-10), monocytic chemoattractant protein-1 (MCP-1), interleukin-4 (IL-4), IL-6, and interleukin-10 (IL-10), some of which can trigger a cytokine storm and atherosclerosis in a host." (PMID 36289895, 2022). "IL-6 is a major contributor to the development of atherosclerosis." (PMID 35598196, 2022). "Considering the fact that inflammation has a key role in the development of atherosclerosis, we further investigated whether capsaicin administration could ameliorate inflammation in ApoE−/− mice, and the levels of IL-1β, IL-6, TNF-α were detected in serum." (PMID 36297020, 2022). "Furthermore, IL-6, a cytokine that induces hsCRP production in the liver, also accelerates inflammation in atherosclerosis." (PMID 36293692, 2022). "However, more data need to be collected to confirm or disprove the clinical efficacy of anti-IL6 agents in preventing atherosclerosis progression." (PMID 36499242, 2022). "IL-6 contributes to the development of atherosclerosis, inflammation, and cardiovascular disease." (PMID 36010052, 2022). "PAR1, like IL-6, plays an important role throughout various stages of atherosclerosis." (PMID 36319844, 2022). "IL-6 is an important source for promoting systemic inflammation in diabetic patients which results in development and progression of cardiovascular complication, particularly arterial atherosclerosis." (PMID 36397128, 2022). "Interleukin-6 (IL-6), another important proinflammatory cytokine has been shown to play a critical role in the development of atherosclerosis and atherosclerotic disease including kidney diseases, and it is well known that patients having CKD are at higher risk for accelerated atherosclerosis." (PMID 35205271, 2022). "In addition, the expression of CAMs, as well as the release of IL-6 or IL-1β from endothelial cells, represents one of the earliest pathological changes in immune and inflammatory diseases such as atherosclerosis." (PMID 35456570, 2022). "As a high hsCRP level has been associated with an increase in proinflammatory cytokines such as IL6, it may sustain chronic inflammation during atherosclerosis progression and heart failure." (PMID 35203703, 2022).
atherosclerosis (continued). "IL-6 may potentiate the initiation and development of atherosclerosis by inducing platelet and coagulation cascade activation, upregulation of adhesion molecules expression, and loss of endothelial layer integrity." (PMID 36555579, 2022). "The relationship between increased IL6 levels and the progression of atherosclerosis is well known." (PMID 35174782, 2022). "Interleukin-6 in atherosclerosis: atherogenic or atheroprotective?" (PMID 35946754, 2022). "Others have shown that IL-1, IL-6, and TNF-a are associated with atherosclerosis in general, and therefore, may be elevated in patients with cardiac or cerebrovascular diseases." (PMID 36582735, 2022). "In addition, H. pylori releases many cytokines, including interleukin-6 (IL-6), tumor necrosis factor-α (TNF-α), IL-1 and free radicals, causing atherosclerosis and oxidative stress." (PMID 35992650, 2022). "Clinical and pre-clinical evidence support the pivotal role of chronic inflammation and endothelial dysfunction in accelerating the process of atherosclerosis, driven by proinflammatory cytokines such as interleukin 6 (IL-6) and tumor necrosis factor alpha (TNF-alpha)." (PMID 36352850, 2022). "On the other hand, IL-6 has an atheroprotective effect because lifetime IL-6 deficiency leads to more severe atherosclerosis rather than inhibition of plaque formation." (PMID 35402550, 2022). "IL-6 synthesized by endothelial cells boosts myelopoiesis and leukocytosis in atherosclerosis." (PMID 35747128, 2022). "Atherosclerosis and thrombosis may be exacerbated by senescent ECs that produce increased levels of IL-1, IL-6, IL-8, IL-15, monocyte chemoattractant protein-1 (MCP-1), TNF, and other mediators." (PMID 36082127, 2022). "Circulating IL-6 is a biomarker for CVD such as acute coronary syndrome with atherosclerosis." (PMID 35600479, 2022). "To determine whether macrophage inflammation is involved in Hcy-related atherosclerosis, we detected F4/80 (a positive marker of macrophages) and proinflammatory cytokines (IL-1β, IL-6, and TNF-α) in the aortic root of ApoE−/− mice." (PMID 34725437, 2022). "Mechanistically it could be demonstrated that raloxifene decreases atherosclerosis by preventing IL-6-induced phosphorylation of STAT3 and inhibiting the IL-6/GP130 interaction." (PMID 35600479, 2022). "TNFα could induce IL6 and IL1β as a cellular signaling molecule attributing to the inflammatory regulation in atherosclerosis, or act as a pro-inflammatory molecule to promote hypertension or atherosclerosis with IL6 and IL1β." (PMID 33318871, 2021). "TMAO drives atherosclerosis progression, in part, by regulating macrophage activation and foam cell formation, platelet activation, and aggregation, resulting in elevated expression of IL-1β, IL-6, and TNFα inflammatory cytokines." (PMID 33562334, 2021). "It is known that ox-LDL, TNF-α, IL-6, and other atherosclerosis stimuli remain at a high level in ACS patients for a long time, which may lead to the adaptive upregulation of the expression and activity of antioxidant enzymes in the affected cells." (PMID 34327240, 2021). "Moreover, aging also leads to a gradual reduction of mitochondrial function and elevated levels of interleukin-6 (IL-6) in the vasculature leading to atherosclerosis." (PMID 34072794, 2021). "Thus, the relationship between HSPs and inflammatory cytokines in atherosclerosis progression needs to be further explored using IL-6 and TNF-alpha knockout mice in the future." (PMID 33782520, 2021). "Malnutrition is closely related to inflammation and atherosclerosis, and through common mediators such as IL-6 or TNF-α, it may play a relevant role in ESA hyporesponsiveness." (PMID 33449974, 2021). "IL-6 is considered an upstream inflammatory cytokine which is a central mediator of the acute-phase response, and is essential to the initiation and progression of atherosclerosis." (PMID 33709785, 2021).
atherosclerosis (continued). "Hence, IL-6, a pro-inflammatory cytokine produced mainly by macrophages can favor the development and progression of atherosclerosis." (PMID 33925692, 2021). "Indeed, both osteoporosis and atherosclerosis have been linked to an overall inflammatory state and the levels of CRP, IL-6, and TNF-α directly correlated to the bone resorptive action of monocytes." (PMID 34610044, 2021). "IL-6 has been identified as a major cytokine that promotes atherosclerosis in apoE–/– mice." (PMID 34901005, 2021). "The release of TNF-α, IL-6, and IL-10 can activate NF-кB to promote the production of inflammatory factors such as IL-8, which further aggravates the inflammatory reaction in the atherosclerosis process." (PMID 34568579, 2021). "The prognostic value was independent of interleukin-6, C-reactive protein, and classical risk factors for atherosclerosis." (PMID 33936385, 2021). "The MIS was positively correlated with age, the number of hospitalizations, the presence of atherosclerosis, ferritin, IL-6, TNF-α, CRP and MIAS and inversely correlated with the BMI, albumin, prealbumin, hemoglobin, transferrin, creatinine and blood phosphorus." (PMID 33413177, 2021). "Chronic inflammation induces the release of pro‐inflammatory cytokines such as tumor necrosis factor‐α (TNF‐α), monocyte chemoattractant protein‐1 (MCP‐1), and interleukin 6 (IL‐6); immune cell infiltration is closely related to the pathogenesis of atherosclerosis in vessel walls." (PMID 34136191, 2021). "According to the authors, fucoidans could ameliorate symptoms of atherosclerosis by downregulating the gene and protein expression levels of IL-6." (PMID 34940677, 2021). "Administration of IL-6 to male mice fed normal or high-fat diets exacerbated atherosclerosis." (PMID 33786327, 2021). "IL6 trans-signaling contributes to sustained inflammation in chronic conditions such as atherosclerosis and experimental research indicate that trans-signaling could be detrimental in the ischemic brain." (PMID 34372806, 2021). "Indeed, the increase in IL‐6 is remarkable and agrees with the importance of this cytokine in atherosclerosis." (PMID 33936566, 2021). "For example, vascular smooth muscle cells senescence can promote atherosclerosis and plaque vulnerability; senescence can also up-regulate the secretion of interleukin 6 (IL-6) and CCL2 production in aortic smooth muscle cells, causing chronic inflammation and promoting atherosclerosis." (PMID 33897463, 2021). "Likewise, IF has benefits in slowing the development of atherosclerosis since it inhibits the development of atherosclerotic plaques by reducing the concentrations of inflammatory markers, such as IL-6, homocysteine, and C-reactive protein." (PMID 34579056, 2021). "Some research has suggested that inflammation plays a role in the process of atherosclerosis, through an increase in the expression of proinflammatory cytokines and adhesion molecules (such as the tumour necrosis factor alpha [TNFα] and interleukin 6 [IL-6])." (PMID 35054229, 2021). "Therefore, in our opinion, high-concentration homocysteine affects the progression of atherosclerosis by increasing the secretion of proinflammatory cytokines secreted by PBMNCs, such as Il-1β, Il-6, RANTES, and by attenuating the secretion of Il-10." (PMID 34771080, 2021). "IL6 is a key moderator of inflammation which has been found to play an important role in the pathogenesis of atherosclerosis, while IL6 gene -174G/C (rs 1800795) and -572G/C (rs 1800796) polymorphisms were related to bone metabolism and BMD among postmenopausal women." (PMID 33478001, 2021). "One study examined the effects of IL-6 on the development of early atherosclerosis in non-obese diabetic male mice and ApoE-deficient mice that were fed a high-fat or normal chow diet for 15 weeks while receiving recombinant IL-6 or saline once a week." (PMID 34071276, 2021).
atherosclerosis (continued). "Furthermore, an increase in ox-LDL, together with high IL-6 levels, has been associated with an increased risk of CVD events and CVD-related mortality in CKD patients in hemodialysis (HD) and accelerated atherosclerosis development observed in CKD." (PMID 35052582, 2021). "IL-6 is abundantly released in the process of atherosclerosis development." (PMID 34356982, 2021). "Inflammation cells, monocytes and cytokines they release (such as TNF-α, IL-1β, IL-6) have also been found to play an important role in different cardiovascular pathological processes, such as atherosclerosis, myocardial infarction, myocardial remodelling and heart failure, and arrhythmias." (PMID 34957244, 2021). "Moreover, elevated IL-6 levels and TNF-α have been associated with the development of atherosclerosis and vascular calcification in CKD patients." (PMID 35052582, 2021). "Some risk factors such as dyslipidemia, oxidized lipids, and cytokines can activate polarization of M1 macrophages that secrete proinflammatory cytokines such as TNF-α, IL-6, IL-1β, and iNOS, thereby creating inflammatory environment and promoting the development of atherosclerosis." (PMID 34901005, 2021). "SOCS3, whose expression level increased continuously along with the elongation of feeding in ApoE−/− mouse aortas, is closely correlated with atherosclerosis progression because it plays a regulatory role in the expression and activation of IL-6, TNF-α, as well as other inflammatory cytokines." (PMID 32169038, 2020). "The IL-6 played a key role in inflammatory response and atherosclerosis." (PMID 33029103, 2020). "L5 may contribute to atherosclerosis by augmenting macrophage foam cell formation, upregulating CD11c expression, or enhancing the expression of inflammatory mediators, such as IL-6, IL-8, and TNF-α." (PMID 32824307, 2020). "Interestingly, patients with atherosclerosis also show significant increases in the number of peripheral Th17 cells and levels of Th17-related cytokines, e.g., IL-6, IL-17, and IL-23." (PMID 32635226, 2020). "However, there is little information about the profile of CpG spots and their methylation status in the promoter of the IL-6 gene in patients with atherosclerosis." (PMID 33123328, 2020). "Second, adipocytokines, i.e. fat-related inflammatory markers such as IL-6 and leptin, play an important role in atherosclerosis including initial activation of endothelial cells, through atherosclerotic progression and, ultimately, its final complication, thrombosis." (PMID 32933542, 2020). "However, low-doses of MTX do not reduce inflammatory factor levels (e.g., interleukin-1β, interleukin-6, or C-reactive protein) and the risk of ASCVD among patients with stable atherosclerosis." (PMID 32576189, 2020). "In addition to IL-1β, IL-6, and TNF-α, other circulating peptides and cytokines are linked to atherosclerosis and cardiovascular disease." (PMID 32485823, 2020). "Furthermore, in the development of both RA and atherosclerosis, the same proinflammatory cytokines, i.e., interleukin (IL)-6 and tumor necrosis factor-alpha (TNF-α), are at work." (PMID 32228568, 2020). "Although atherosclerosis is often associated with high inflammatory markers, we did not observe differences in circulating hsCRP and IL-6—among other markers of inflammation and endothelial dysfunction—between PA patients and EHT controls." (PMID 31875423, 2020). "IL–6 is known to be involved in the inflammatory processes of atherosclerosis." (PMID 32349742, 2020). "By contrast, at an early stage, deletion of the IL6 gene in apoE-deficient mice did not affect the disease relative to control mice, whereas at later stages, this knockout promoted atherosclerosis." (PMID 32121175, 2020).